IDO1 (indoleamine 2,3-dioxygenase 1)
Diseases named in the same sentence as IDO1 in open-access papers (continued):
Sharing a sentence is not in itself a finding about the gene and the disease.
infection (continued). "However, the data presented here shows how increased IDO-1 activity and inflammatory responses are related to the distinct phases of infection, and this, therefore, contributes to the understanding of the mechanisms underlying chikungunya pathogenesis." (PMID 35456119, 2022). "Furthermore, infection can upregulate the expression of indoleamine 2,3-dioxygenase 1 (IDO1) in IECs, promote mucus production in goblet cells and increase the proportions of Akkermansia muciniphila and Mucispirillum schaedleri via AhR and Notch signals." (PMID 35155283, 2022). "After infection by T. gondii, IDO1 levels decline, presumably resulting in reduced levels of KYN." (PMID 34095234, 2021). "Knockdown of Prdm1 in IEC4.1 cells resulted in enhanced antimicrobial activity against C. parvum infection induced by IFN-γ, with a significant further decrease in the infection burden and a further increase in the expression of defense genes, including Nos2, Ido1, and Csf2." (PMID 34488445, 2021). "There have been no previous reports as to the role of IDO1 during infection in A549s and as such we generated an IDO1 deficient A549 cell line and challenged with CTG-GFP in the presence of IFNγ." (PMID 34871166, 2021). "On the other hand, IDO1 may contribute to the uncontrolled proliferation of M. tuberculosis at late stages of infection in pMT-10 mice with high levels of IFN-γ and with necrotic lesions." (PMID 34554927, 2021). "One of the upregulated genes was ido1, a known infection- and interferon-induced host gene." (PMID 34819931, 2021). "Previous studies have found increases in the expression of indoleamine 2,3-dioxygenase 1 (IDO1) associated with intestinal flora and the differentiation of gut secretion cells is related to inflammation, injury, infection, changes in flora, and so on, but with reduced SLC2A5 levels." (PMID 34604392, 2021). "In addition, IFN-γ strongly induces the activation of the tryptophan degradation pathway, mediated by IDO1, and a large body of evidence indicates that the tryptophan catabolism pathway is involved directly or indirectly in the host response to infection." (PMID 32256470, 2020). "We observed, IDO1 promoter activity is supported by β-catenin during infection." (PMID 30770800, 2019). "The antibacterial effect could be ascribed to IDO1-mediated tryptophan degradation, since the supplementation of l-tryptophan at the timepoint of infection allowed an unrestricted bacterial growth." (PMID 31267172, 2019). "Nevertheless, IDO1, the first rate-limiting enzyme in kynurenine metabolism, is upregulated in murine BMDMs upon infection with M.avium, however, its deficiency does not impact on the outcome of the infection." (PMID 30374347, 2018). "In addition, T. gondii numbers per vacuole at 24 h post infection in IDO1-KO cells were higher than in wild-type cells, whereas the infection rates were comparable." (PMID 30283439, 2018). "In addition, both MV-Edm infection or CD8+NKG2D+ transfer alone also induced IDO1, however, to a lesser extent." (PMID 28701757, 2017). "Thus, after 96 h, 2, and 10 weeks of infection with yeasts, the lung infiltrating leukocytes from the IDO1−/− and WT mice were obtained, and the presence of intracellular IDO1 and AhR in CD11b+ and CD11c+ cells detected by flow cytometry." (PMID 28791025, 2017). "In addition, high expression of Ido1 can downregulate the inflammatory response exhibited by M. fortis after infection with S. japonicum." (PMID 28900150, 2017). "In the SIV-infected spleens, SOCS3 expression was shown to be highly expressed not only during acute infection but also throughout asymptomatic and chronic infection, demonstrating a strong potential reason for the suppression of IDO1 despite abundant virus stimuli during chronic infection." (PMID 28066416, 2016).
infection (continued). "The selected targets included genes that were differentially expressed in both gt1‐ and gt3‐infected samples versus controls (CXCL9, IFIT1, ISG15 and RSAD2), as well as genes that were differentially regulated only in gt1 infection (USP18) or gt3 infection (IDO1)." (PMID 25800823, 2015). "An antibacterial and antiparasitic role of endothelial IDO1 may be anticipated, and this might contribute to protection of the feto-placental unit against infection." (PMID 24904580, 2014). "Monocytes, infected with serovars Ba and D expressed higher levels of IDO 1 day post infection." (PMID 25123797, 2014). "Thus, IDO1, promptly induced in infection, is apparently required for local immunoregulation via IL-10+ Treg cells." (PMID 23853597, 2013). "An opposite pattern of resistance was observed in IDO1-deficient mice, in which resistance to infection was increased early but not late in infection." (PMID 23853597, 2013). "Rates of virus clearance were unaffected by IDO1 gene ablation but virus titers in lungs trended lower (though were not statistically significant) in IDO1-KO mice (×101) relative to WT mice, suggesting that IDO may impede host control during X31 infection." (PMID 23785507, 2013). "We found elevated levels of IL-22 through the infection in IDO1-deficient mice in which high levels of IL-17F, but not IL-17A, were also higher as compared to wild-type mice." (PMID 23853597, 2013). "Recently, our group demonstrated that inhibition of increased IDO1 activity attenuates Toxoplasma gondii replication in the lung, and the inflammatory damage is significantly decreased by the administration of the IDO1 inhibitor after infection." (PMID 23476103, 2013). "The increased resistance seen later in infection in IL-22-deficient but not IDO1-deficient mice, prompted us to define mechanisms of resistance that are independent from IL-22 but dependent on IDO1." (PMID 23853597, 2013). "When such concept is applied to a scenario of infection, it seems that IDO1 activation in some certain settings may contribute to ineffective development of adaptive immunity and allow a microorganism to persist." (PMID 22860140, 2012). "Nevertheless, further investigation is warranted to see whether IDO1 activation upon the infection also leads to tolerogenic responses or other modulation of the immune system." (PMID 22860140, 2012). "Furthermore, the numbers of antigen specific T cells that produced IFN-γ in response to secreted M. tuberculosis antigens were equivalent in WT and IDO-1−/− mice throughout the course of infection." (PMID 22649518, 2012). "Activation of IDO1 by IFN- γ resulted in a lower number of OT load in THP-1 macrophages, and the degree of infection could be partly restored by an inhibitor of IDO1 enzyme." (PMID 22860140, 2012). "Similarly, we observed an increase in IDO-1 mRNA expression in murine bone marrow-derived macrophages (mBMDM) upon infection with M. tuberculosis." (PMID 22649518, 2012). "For example, 3-hydroxy-kynurenine, a subsequent product of IDO1 activation, was found to limit replication of Trypanosoma cruzi in vivo; treatment of the infected mice with the metabolite can improve resistance to the infection as well as survival of the host." (PMID 22860140, 2012). "In addition to immune tolerance, this pathway also plays other roles, such as anti-infection, and umbilical vein endothelial cells can express IDO1, which results in antibacterial and anti-parasitic effects, helping to protect the fetus-placental unit from infection." (PMID 40278627, 2025). "Additionally, the increased expression of IDO1 during Trp metabolism suggests IDO1 may have a previously unrecognized role in 17ZR101-infection." (PMID 40096073, 2025). "Thus, IDO1 expression has been shown to be upregulated during T. cruzi infection in mice, resulting in its activity being critical to controlling this parasite replication during the acute phase of infection." (PMID 39119291, 2024).
infection (continued). "By detecting the transcription levels of the gene encoding IDO (ido1) in the brain, we found that there was still a significant upregulation trend of IDO1 in the Lactobacillus transplantation group during the non-acute infection period." (PMID 38956725, 2024). "Therefore, we investigated whether Mtb influences the expression of chemokines by upregulating IDO1 expression in macrophages, thereby reducing T-cell infiltration at the site of infection." (PMID 39438693, 2024). "Similarly, in the mammary gland, IDO1 may contribute—together with other antibacterial factors of the milk—to tissue protection against infection and inflammation." (PMID 39061522, 2024). "The expression and activity of IDO1 during infection were maintained stably greater at night than during the day in CF mice, as well as levels of Foxp3, Il10 and Tgfb gene expression, which may explain the reduced inflammatory damage and PMN recruitment in mice infected at ZT12." (PMID 36896128, 2023). "Also, a decreased number of IDO-1-producing M-MDSCs was observed after two weeks of infection." (PMID 37524886, 2023). "However, IDO-1 deficiency fails to impact immune control and infection outcome in the mouse model of TB." (PMID 35045867, 2022). "It is worth noting here that the concentration of tryptophan used in the media for these experiments (16 μg/ml) was higher than what has been used previously to observe IDO1-mediated infection restriction, which may prevent IDO1-mediated depletion of tryptophan." (PMID 34871166, 2021). "In addition, IDO1 was differentially expressed during different C. trachomatis infection statuses, with the highest levels observed in women post antibiotic treatment and during repeated infection." (PMID 30832593, 2019). "Furthermore, we could ascribe the IFN-γ-induced antiparasitic effect to IDO1, since we found that tryptophan supplementation at the timepoint of infection results in a nearly complete recovery of T. gondii ME49 tachyzoite growth." (PMID 31267172, 2019). "IDO1 activity can limit the replication of intracellular pathogens to prevent dissemination, however, is typically not sufficient to kill intracellular microbes and without the participation of other cell autonomous defense pathways, can lead to persistent infection of infected tissues." (PMID 31461509, 2019). "Thus, this study identifies IDO1 production as a key cell-autonomous defense mechanism that limits infection by C. burnetii, which suggests that peptides derived from hydrolysis of proteins in the CCV do not provide an adequate supply of tryptophan for bacterial replication." (PMID 31461509, 2019). "mice and IDO inhibitor to examine whether IDO1 is an important factor for immune regulation against LP-BM5 infection and especially whether the presence of IDO1 is necessary for the induction of cytokines and IDO1-related molecules, which are important for viral clearance." (PMID 23476103, 2013). "Furthermore, infection with P. aeruginosa resulted in a higher Kyn:Trp ratio in the lungs of the dysbiotic WT mice than in the lungs of the eubiotic WT mice (p = 0.0004), suggesting that IDO1 may be more active in the former group." (PMID 40387573, 2025). "It is consistent with prior observations in highly virulent PRRSV-1 Lena infections, where CTLA4 expression was upregulated to a greater extent than CD28 expression in PRRSV-infected lung, indicating an imbalance favoring IDO1 induction." (PMID 40459260, 2025). "To further investigate the impact of IDO1 on the formation of NETs, we analysed NET expression in mice before and after infection with E. multilocularis using various methods." (PMID 40597301, 2025). "This increased susceptibility observed in dysbiotic mice correlates with increased IDO1 enzyme activity and AHR activation, which impair phagocytosis of P. aeruginosa and promote exacerbation of infection." (PMID 40387573, 2025).
infection (continued). "The results revealed that IDO1 levels increased with both the Mtb multiplicity of infection (MOI) and the duration of infection." (PMID 39438693, 2024). "The results showed that infection of these ZIKV strains also induced mRNA and protein expression of TRIM22, which is consistent with other ISGs, such as MX1, IDO1 and RSAD2." (PMID 36042495, 2022). "Our findings demonstrated that the acute phase of CHIKV infection was characterized by increased IDO-1 activity and inflammatory responses in CHIKV-infected patients, suggesting an important role in the innate antiviral response during infection." (PMID 35456119, 2022). "Transduction titers of amphotropic MLV-based vector in HeLa/FAT10, HeLa/IDO1, and HeLa/IFI6 cells were also lower than those in HeLa/empty cells, which shows that FAT10, IDO1, and IFI6 inhibit MLV-based vector infection as well as HIV-1-based vector infection." (PMID 35883685, 2022). "With regard to gene expression analysis by overlapping along infection, transcripts deemed relevant to VL, such as ARG1 and IDO1, exhibited high expression at 60, 120 and 150 dpi." (PMID 34804009, 2021). "The marked upregulation of IDO1 (almost 102 fold change) in HVL-VIA and HVL-MEC fetuses is indicative of the infection of the HRT." (PMID 33933084, 2021). "It was described that IDO1 and NOS2 are co-expressed as a result of infection or inflammation in human tissues." (PMID 33807310, 2021). "Differently from HeLa cells and possibly due to infection-induced type-I IFN production, C. trachomatis infection significantly increased the IDO1 expression in IFNG-treated HL-60 cells compared to IFNG-only-treated cells." (PMID 34819931, 2021). "Of note, while IDO-1 drives AHR activation in the context of other infections, MHV induced a similar expression level of downstream genes in wild-type and IDO-1-/- macrophages, suggesting that additional pathways besides IDO-1 are involved in AHR activation." (PMID 33746961, 2021). "Surprisingly, we found that in women that had a single infection (CT-P), after antibiotic treatment and infection clearance (PAT), IDO1 expression levels increased significantly (p = 0.0148)." (PMID 30832593, 2019). "We found that similar to IDO1 expression levels, women with repeated C. trachomatis infections had significantly higher TGF-β1 levels, as well as in women who cleared their infection post antibiotic treatment." (PMID 30832593, 2019). "Here, we have focused on a selection of immune genes, IDO1, IFN-γ, TGF-β1 and FoxP3, to examine the regulatory immune response during C. trachomatis single versus repeated infection and post antibiotic treatment, in a cohort of a previously published study." (PMID 30832593, 2019). "Taken together, these data showed that infection of THP-1 cells with GRA15-intact T. gondii produced IL-1β in a manner dependent on NLRP3 and caspase-1; this led to an indirect reduction in IDO1 proteins, thereby supporting parasite growth in human cells." (PMID 30301855, 2018). "Upon infection with MCMV, both WT and IDO1-KO mice showed severe wasting and presented with fever at day 2 post-infection." (PMID 26914138, 2016). "IDO-1 mRNA and protein expression were also increased in IFN-γ-stimulated human monocyte-derived macrophages (hMDM) in response to infection with M. bovis BCG." (PMID 22649518, 2012). "In mice, infection with Mycobacterium bovis, Bacille Calmette Guerin (BCG) lead to increased IDO-1 activity as indicated by elevated levels of kynurenine in serum, lung and brain." (PMID 22649518, 2012). "When IDO1 activity in IFN-γ treated cultures was inhibited by 1-MT, the infection index was partially restored." (PMID 22860140, 2012). "This pathogen-exploitable mechanism is not exclusive to SARS-CoV-2; several viruses leverage the IDO1-KYN-AHR axis to facilitate infection and evade host immune defences." (PMID 40949107, 2025).
infection (continued). "Here, IDO1‐mediated kynurenine production and the AHR activation pathway were shown to impair P. aeruginosa infection by interfering with bacterial phagocytosis and preventing neutrophil recruitment to the infection site." (PMID 40387573, 2025). "However, the expression of IDO1 in the IDO+ TNF+ ISG subcluster was pustule-specific, suggesting that active IFN-γ-dependent signaling occurred during infection." (PMID 39882906, 2025). "Notably, IL-6 levels negatively correlated with CTLA4 and IDO1 expression, particularly in JBNU-22-N01 infection." (PMID 40459260, 2025). "With IFNγ blockade, genes in cluster 2, including IL18R1, IDO1, CXCL11, CD274 (PD-L1), and PTPN2, were similarly expressed at day 3 post-infection but were more highly expressed at day 7 compared to controls and had increased expression over the day 3 timepoint." (PMID 38950078, 2024). "Inspection of key DE genes, irrespective of AM donors and infection time points, replicates the finding of substantial inter-individual differences, for example IDO1 and its co-expressed genes." (PMID 37333188, 2023). "While the function of GBP family members in infection with C. burnetii has not yet been addressed, a recent study reported that IDO1 impairs growth of C. burnetii in human THP1 macrophages." (PMID 36479617, 2023). "At ZT12, despite the high basal level, Ido1 was not further induced and remains constant during infection." (PMID 36896128, 2023). "The high levels of PD-L1 and IDO1 observed in the near absence of PD-1 offers clues into how an immunoregulatory niche during infection is initiated and maintained." (PMID 35058616, 2022). "More importantly, the tolerogenic phenotype of DCs is partly reverted in IDO1-/- mice, as indicated by enhanced activation, proliferation, and differentiation of both CD4+ and CD8+ - T cells upon infection with Echinococcus multilocularis, in comparison with WT mice." (PMID 36439161, 2022). "Therefore, in this study we determined the IDO-1 activity, and cytokine and chemokine patterns in CHIKV-infected patients during acute, post-acute, and chronic phases of infection." (PMID 35456119, 2022). "Transduction titers on the FAT10-, IDO1-, and IFI6-expressing HeLa cells (HeLa/FAT10, HeLa/IDO1, and HeLa/IFI6 cells) were much lower than those on the control cells, showing that FAT10, IDO1, and IFI6 significantly inhibit amphotropic MLV-pseudotyped HIV-1-based vector infection." (PMID 35883685, 2022). "However, transduction titers in HeLa/IDO1/shAtg3 cells were lower than those in HeLa/shAtg3 cells, showing that IDO1 expression inhibited HIV-1-based vector infection in the Atg3-silenced cells." (PMID 35883685, 2022). "Additionally, increased levels of IDO-1 expression were also seen in the brain of A129 mice infected with ZIKV, 5 days upon infection, peak of disease manifestation in these mice, when compared to Mock littermates." (PMID 34335614, 2021). "To test whether IDO1 was functional, we performed a UHPLC–MS/MS analysis of the uninfected/untreated and infected and/or IFNG treated HL-60 and HeLa cells at 24 h post-infection." (PMID 34819931, 2021). "Overall, the results show that IDO-1 inhibition was not able to reduce clinical manifestations induced by ZIKV-infection, as well as virus replication in A129 mice." (PMID 34335614, 2021). "The HVL-VIA group had a significant upregulation of IDO1, consistent with PRRSV-infection." (PMID 33933084, 2021). "Our findings demonstrate that IDO1 does not impact infection in A549s at least under the conditions used in this study." (PMID 34871166, 2021). "Mice were also shown to be more vulnerable to infection by A. fumigatus fungi lacking IDO, while mice without IDO1 displayed a similarly increased susceptibility to infection." (PMID 34095234, 2021). "We found it curious that IDO1 was not identified by this screen considering its significant impact on infection observed in some but not all cell lines." (PMID 34871166, 2021).